GPR32P1 (GPR32 pseudogene 1)
Description:
Orphan receptor.
Synonyms: formerly GPR32P
Gene: Unprocessed pseudogene on chromosome 19 (50,758,382 to 50,759,192, forward strand). Ensembl gene ENSG00000269565.
Subcellular location: Cell membrane